APOA1 (apolipoprotein A1)
Diseases named in the same sentence as APOA1 in open-access papers (continued):
Sharing a sentence is not in itself a finding about the gene and the disease.
schizophrenia (14 papers, 2013 to 2025). A major psychotic disorder characterized by abnormalities in the perception or expression of reality. "Genetic polymorphisms, particularly those of the APOA1 gene, were associated with a variation in the dyslipidaemic effect experienced by patients with schizophrenia treated with AAs." (PMID 41017289, 2025). "The association between serum ApoA1 and ApoB levels and clinical symptoms in patients with schizophrenia was regulated by the presence of ApoE rs429358 polymorphism." (PMID 34930329, 2021). "For patients with schizophrenia, both ApoA1 and ApoB levels were positively associated with cognition." (PMID 34135129, 2021). "There was a significant association between ApoA1 or ApoB levels and cognition in schizophrenia, which was regulated by the ApoE rs429358." (PMID 34135129, 2021). "We speculated that ApoE polymorphism rs429358 may be involved in the development of schizophrenia and further the relationship between the clinical symptoms and the ApoA1 or ApoB levels in patients with schizophrenia." (PMID 34930329, 2021). "Therefore, the observed relation between ApoE variant status and alterations in ApoA1 levels is specific for patients with schizophrenia." (PMID 34930329, 2021). "Furthermore, the association between ApoA1 or ApoB levels and psychopathology of schizophrenia was regulated by ApoE rs429358." (PMID 34930329, 2021). "The APOA1 75G/A was associated with higher triglyceride levels and lower HDL levels in patients with schizophrenia treated with AAs." (PMID 41017289, 2025). "PI (16:0/20:4) and TNC were decreased in the prefrontal cortex of schizophrenia samples, while APOA1 was increased." (PMID 37143779, 2023). "A meta-analysis between schizophrenia patients and healthy controls was performed, with the results suggesting four apolipoproteins, APOA1, APOA2, APOC1 and APOC3 (downregulated), and ficolin-3 (upregulated) as potential biomarkers of the disorder." (PMID 35563307, 2022). "In all selected studies where it was identified as altered, ApoA1 level was reported to be reduced in schizophrenia patients compared to healthy subjects." (PMID 35563307, 2022). "A large number of studies have observed changes in the levels of ApoA1 and ApoB in patients with schizophrenia, with mixed results, such as elevated ApoA1 or ApoB, which can be used as biomarkers of schizophrenia as well as decreased ApoA1 or ApoB." (PMID 34930329, 2021). "On the one hand, numerous studies have observed the mixed changes in ApoA1 and ApoB levels in patients with schizophrenia, such as an increase in ApoA1 or ApoB and reduction of ApoA1, or ApoB." (PMID 34135129, 2021). "Compared to healthy individuals, patients with schizophrenia exhibited a decrease in ApoA1 levels." (PMID 39457610, 2024). "This study found that the levels of ApoA1 and ApoB were negatively associated with negative symptoms of patients with schizophrenia." (PMID 34930329, 2021). "First, owing to the cross-sectional study design, the causality between ApoE rs429358, ApoA1 and ApoB levels, clinical symptoms in patients with schizophrenia was not directly presented." (PMID 34930329, 2021). "However, the serum ApoA1 and ApoB levels were positively correlated with the degree of cognitive function in patients with schizophrenia, indicating that serum ApoA1 and ApoB levels may be biomarkers of general cognitive function in schizophrenia patients." (PMID 34135129, 2021). "Our study found that ApoA1 and ApoB levels were positively associated with PANSS negative symptoms in patients with schizophrenia." (PMID 34930329, 2021). "ApoA1 is the main protein component of HDL, and a biomarker of cardiovascular disease, while ApoB is the main protein including plasma chylomicrons, very-low-density lipoprotein (VLDL) and LDL, which can be used as a biomarker of schizophrenia." (PMID 34135129, 2021).
schizophrenia (continued). "Our study found that ApoE rs429358 genotype groupings had a significant effect on the relationship between serum ApoA1 or ApoB levels and negative symptoms of schizophrenia." (PMID 34930329, 2021). "A significant correlation between PANSS negative symptoms and ApoA1 levels (p = 0.048) or ApoB levels (p = 0.001) was found in patients with schizophrenia, which was also confirmed by linear regression analyses (p = 0.048 vs. p = 0.001)." (PMID 34930329, 2021). "These consistent results may suggest that the impacts of ApoA1 and ApoB levels on cognitive function may not be affected by schizophrenia." (PMID 34135129, 2021). "Thus, ApoE genotype may play a role in conferring negative symptoms in schizophrenia by affecting ApoA1 or ApoB levels." (PMID 34930329, 2021).
cerebral amyloid angiopathy (13 papers, 2014 to 2026). "Research has shown that peripheral overexpression of human apoA1 preserves cognitive function, reduces neuroinflammation, and protects against cerebral amyloid angiopathy in mice, suggesting a direct role for peripheral small functional HDL particles in brain amyloid-beta clearance." (PMID 41109840, 2026). "However, the main effects of ApoA1 could be mainly reflected on cerebrovascular Aβ accumulation, known as cerebral amyloid angiopathy (CAA), which is an early phenomenon in AD pathophysiology." (PMID 32466344, 2020). "Previous studies have shown that overexpression of human ApoA1 in the circulation can prevent learning and memory impairment in APP/PS1 transgenic mice, partly by reducing neuroinflammation and cerebral amyloid angiopathy." (PMID 39484667, 2022). "Overexpression of human ApoA1 in circulation was shown to prevent learning and memory impairments in APP/PS1 transgenic mice, partly by suppressing neuroinflammation and cerebral amyloid angiopathy." (PMID 35782939, 2022). "In contrast, transgenic mice (APP/PS1) lacking ApoA1 showed increased amyloid deposition and astrogliosis in the cerebral cortex, as well as the development of cerebral amyloid angiopathy." (PMID 41516203, 2025).
hereditary amyloidosis (13 papers, 2011 to 2024). Hereditary amyloidosis refers to a group of inherited conditions that make up one of the subtypes of amyloidosis. "Indeed, patients presenting mutations of the ApoA1 gene are more at risk of developing ApoA1 hereditary amyloidosis." (PMID 32456156, 2020). "Particular mutations in the Apolipoprotein A-I (APOA1) gene provoke hereditary amyloidosis." (PMID 31405050, 2019). "This becomes especially important, if the gene under study has pleiotropic effects, i.e. affects multiple phenotypic traits, as is the case for APOA1: mutations in APOA1 have been associated with an inability to activate LCAT and with hereditary amyloidosis." (PMID 23209431, 2012).
cerebrovascular disease (12 papers, 2009 to 2025). "APOB/APOA-1 is currently recognized as one of the biomarkers for predicting cardiovascular and cerebrovascular disease risk." (PMID 40573187, 2025). "It should be noted that in recent years, ApoA1 has been increasingly recognized as a protective factor against cardiovascular and cerebrovascular diseases." (PMID 41516203, 2025). "Moreover, although apoA1 and HDL cholesterol levels seem to have a similar association with the risk of cerebrovascular disease, when the levels of LDL cholesterol and triglycerides are added to the model, the associations can be impacted." (PMID 37372137, 2023).
heart failure (12 papers, 2016 to 2026). Inability of the heart to pump blood at an adequate rate to meet tissue metabolic requirements. "The ApoB/ApoA1 ratio had a significant causal relationship with the incidence rate of heart failure in IVW and MR-PRESSO analysis (IVW, OR = 1.090, 95%CI = 1.012,1.174, PFDR=0.038; MR-PRESSO, PFDR=0.045), however, P-values were greater than 0.05 in MR Egger and Weighted median results." (PMID 38310324, 2024). "The ratio of the serum levels of ApoB: ApoA1 is associated with the severity of CVD, including the risk of aortic stenosis, and is predictive for mortality in patients with heart failure." (PMID 38479648, 2024). "Peptides for the Apolipoprotein AI (APOA1) protein were the most significantly differentially expressed between non‐HF and heart failure patients (P = 0.013 and P = 0.046)." (PMID 33779078, 2021). "Another study also found that APOA1 was significantly differentially expressed between non-heart failure and heart failure patients, and could be a candidate blood protein biomarker of heart failure." (PMID 35433888, 2022). "First, we observed that PCS-enriched individuals were likely to have better exercise capacity (muscle mass), whereas those enriched TCS species were likely to have higher risks of heart failure (BNP marker), cardiovascular diseases (ApoA1), and immune disorders (Erythrocyte counts)." (PMID 39245657, 2024).
multiple sclerosis (12 papers, 2009 to 2025). A progressive autoimmune disorder affecting the central nervous system resulting in demyelination. "Receptor for advanced glycation end products and Apolipoprotein A1 (Apo-AI) have been recommended to have a pathogenic role in the neuroinflammatory disorder as multiple sclerosis." (PMID 35140322, 2022). "The APOA1 -75G/A promoter polymorphism was associated with cognitive performance in multiple sclerosis." (PMID 26537097, 2015). "A case–control study found an association of the APOA1 -75G/A promoter polymorphism with cognitive performance in multiple sclerosis." (PMID 24209603, 2013). "Other overlapping proteins were deregulated in multiple sclerosis (MS), PD, and AD including apolipoprotein A1 (Apoa1)." (PMID 40545497, 2025). "In the CNS, ApoA1 may be a marker of neural degeneration and increased CSF concentrations have been seen in patients with AD, Parkinson's disease and multiple sclerosis." (PMID 24260563, 2013). "This is interesting, since ApoA1 is believed to be a marker of neural degeneration and increased CSF concentrations have been seen in patients with neurodegenerative disorders such as AD, Parkinson's disease and multiple sclerosis." (PMID 24260563, 2013).
prostate carcinoma (12 papers, 2015 to 2026). A carcinoma that arises from epithelial cells of the prostate gland. "The underlying mechanism may be that decreased HDL and ApoA1 can result in the inflammation and further contribute to the prostate cancer progression." (PMID 36506554, 2022). "The distinction suggests that more experiments require to be carried out to figure out the mechanism of ApoA1 in prostate cancer." (PMID 36506554, 2022). "Over-expression of ApoA1 in prostate cancer can result from the aberrant metabolism of lipids, which enhances cell proliferation, invasion and induces resistance to the hormonal treatment." (PMID 36506554, 2022). "Moreover, it is also indicated that up-regulation of ApoA1 can be induced by over-expressed MYC in prostate cancer cells, which suggests a possible reason for the aggravation of the disease." (PMID 36506554, 2022). "Nevertheless, a Swedish Apolipoprotein Mortality Risk (AMORIS) study shows a different result, which is that a low level of ApoA1 and HDL may be a risk factor for prostate cancer patients." (PMID 36506554, 2022). "And FAO, ATP level and cell growth increasing in sh-Sun2-downexpressing prostate cancer cells could be reversed by SAA1 interference Serum amyloid A protein (SAA) is an apolipoprotein that can replace apolipoprotein A1 (apoA1) as the major apolipoprotein of high density lipoprotein (HDL)." (PMID 29163775, 2017).
psoriasis (12 papers, 2013 to 2025). An autoimmune condition characterized by red, well-delineated plaques with silvery scales that are usually on the extensor surfaces and scalp. "The authors concluded that the ApoB/ApoA1 ratio is the best predictor of CVD risk in psoriasis." (PMID 40137160, 2025). "In conclusion, our study highlights significant differences in serum apolipoproteins between patients with severe and mild psoriasis, with disease severity correlating negatively with the ApoA1/ApoA2 ratio." (PMID 40137160, 2025). "The aim of this study was to evaluate the potential associations between serum concentrations of apolipoproteins (ApoA1, ApoA2, ApoB, ApoC1, ApoC3, ApoD, ApoE, ApoH, and ApoJ) and various clinical and biochemical markers in patients with psoriasis." (PMID 40137160, 2025). "Further research is needed to confirm the potential of ApoA2 or ApoA1/ApoA2 ratio as a biomarker for metabolic dysregulation in psoriasis patients." (PMID 40137160, 2025). "Until now, most research on apolipoproteins in psoriasis has focused on ApoA1 and ApoB, primarily because of their well-established roles in cardiovascular risk and lipid metabolism." (PMID 40137160, 2025). "While limited prior research has primarily focused on apolipoproteins such as ApoA1, ApoA2, ApoB, ApoC1, ApoC3, and ApoE in psoriasis, our study uniquely extends this scope by also evaluating ApoD, ApoH, and ApoJ in this patient population for the first time." (PMID 40137160, 2025). "No significant genetic correlation and causal relationship was found between lipidemic traits (HDL, LDL, TG, TC, apoA1, apoB, apoE) and psoriasis." (PMID 38550599, 2024). "In conclusion, inflammation in psoriasis can increase serum hCRP levels, resulting in the reduction of anti-atherogenic lipid ApoA1 and increase of pro-atherogenic lipid ApoB." (PMID 34996506, 2022). "The ratio of ApoB to ApoA1 was significantly downregulated in male patients with psoriasis after MTX treatment, indicating that the role of MTX on CVD and other concomitant diseases might be related to sex." (PMID 34996506, 2022). "However, the effect of MTX on some lipid profiles (ApoA1, HDL-C, LDL, TG) was associated with sex and psoriasis subtype." (PMID 34996506, 2022). "While ApoA1 and ApoB in psoriasis have been the primary focus of research due to their established roles in lipid metabolism and cardiovascular risk, other apolipoproteins, such as ApoA2, ApoC1, ApoC3, ApoD, ApoE, ApoH, and ApoJ, have not been widely studied in psoriasis." (PMID 40137160, 2025). "The F-statistic value for the instrument–psoriasis link was 15.996 in the HDL, LDL, apolipoprotein A1, and apolipoprotein B model and 16.533 in the lipoprotein A model." (PMID 37755256, 2023). "Stepwise regression analysis found a positive correlation between the inflammatory marker hCRP and the Psoriasis Area Severity Index (PASI), ApoB/ApoA1 ratio, BMI, and smoking." (PMID 34996506, 2022). "We also observed a negative association between the Psoriasis Area and Severity Index (PASI) and ApoA1/ApoA2 ratio in the patients before the treatment." (PMID 40137160, 2025). "The subgroup analysis for the presence or absence of psoriatic arthritis showed that serum ApoA1 was significantly decreased in psoriasis both with and without arthritis, whereas serum ApoB was significantly increased in psoriasis with and without arthritis." (PMID 40137160, 2025). "Regarding lipidemic traits, we did not observe any significant genetic correlation with psoriasis (apoA1: rg=-0.03, p=0.261; apoB: rg=-0.02, p=0.615; apoE: rg=0.09, p=0.721; HDL: rg-0.05, p=0.077; LDL: rg=-0.04, p=0.344; TC: rg=0.08, p=0.164; TG: rg=0.06, p=0.053)." (PMID 38550599, 2024). "However, no causal effect of psoriasis on HDL cholesterol (OR: 0.997, 95% CI: 0.989–1.006, p = 0.534) and apolipoprotein A1 abnormalities (OR: 0.994, 95% CI: 0.986–1.002, p = 0.142) was determined using the random-effect IVW method." (PMID 37755256, 2023).
type 1 diabetes (12 papers, 2009 to 2026). "In fact, it may be that this rapid aging of ApoA-1, a key protein in lipoprotein metabolism, causes a higher risk of macrovascular disease in persons with type 1 diabetes." (PMID 24688629, 2014). "In patients with type 1 diabetes, lower 25(OH)D3 was significantly correlated to lower apolipoprotein-A1 and IGF-1 Z-score, and higher ALAT activity, GFR, and plasma glucose." (PMID 38084202, 2023). "Apolipoprotein A1 was significantly higher in patients with type 1 diabetes – an observation in line with previous reports, and the Apolipoprotein B/Apolipoprotein A1 quotient was lower." (PMID 38084202, 2023). "Compared to nondiabetic controls, apolipoprotein A1 was significantly higher, and apolipoprotein B and the ratio Apolipoprotein B/Apolipoprotein A1 were significantly lower in patients with type 1 diabetes." (PMID 38084202, 2023). "High apolipoprotein A1 in type 1 diabetes may be due to exogenous insulin." (PMID 38084202, 2023).
Autoimmunity (11 papers, 2010 to 2025). The occurrence of an immune reaction against the organism's own cells or tissues. "The membrane stabilizing scaffold being used to assemble the nanodisc is derived from human ApoA1, thus our immunogens can result in eliciting self-antibodies and can cause autoimmunity." (PMID 38005987, 2023). "The observed association of FRCL3 with anti-apoA-1 IgG values in our sample is in line with previous studies showing that two-thirds of candidate loci for autoimmunity discovered by GWAS represent shared risk factors for multiple ADs." (PMID 28458671, 2017). "Our findings indicate that preclinical autoimmunity to anti-apoA-1 IgG may represent a novel mortality risk factor." (PMID 28458671, 2017). "Between the apolipoproteins, APOA1 is the most abundant protein, and lipid-free APOA1 favored Treg expansion in a murine model of autoimmunity." (PMID 37579971, 2023). "Our findings indicate that preclinical autoimmunity to apoA-1 may identify a substantial proportion of individuals at increased risk of death in the general population, a finding that will need further validation in independent, prospective cohorts." (PMID 28458671, 2017). "Our results extend previous findings and suggest that preclinical autoimmunity against apoA-1/HDL—which affects up to one-fifth of the general population—may identify individuals at increased risk of death." (PMID 28458671, 2017). "In conclusion, this report reveals that in a subset of IRD patients exposed to a SARS-CoV2 infection, humoral autoimmune response against the c-terminal region of ApoA-1 can occur, extending the concept that exposure to infectious agents may lead to the development of autoimmunity in IRD patients." (PMID 37234173, 2023). "ApoA1 is the main protein component of high-density lipoproteins (HDL), and although HDL has a protective role in cardiovascular disease and it has been widely studied, more recent evidence suggests HDL may contribute to kidney disease and autoimmunity." (PMID 35626799, 2022).
fibrosis (11 papers, 2006 to 2023). the formation of excess fibrous connective tissue in an organ or tissue in a reparative or reactive process. "The silica mouse model may be suitable as a chronic fibrosis model for investigating the efficacy of ApoA1 in preventing ongoing lung fibrosis or treating established fibrosis." (PMID 23409054, 2013). "When compared to alcoholic liver disease the decrease of apolipoprotein A1 was not significant in patients with advanced fibrosis and NAFLD." (PMID 16503961, 2006). "However, concerning ApoA1, an increase in alcohol consumption would have been associated with an increase in ApoA1 in the “NAFLD-Serum” cohort, which included 78% of subjects without advanced fibrosis." (PMID 35327501, 2022).